ARID1A (AT-rich interaction domain 1A)
Diseases named in the same sentence as ARID1A in open-access papers (continued):
Sharing a sentence is not in itself a finding about the gene and the disease.
tumor (continued). "A total of 97 (85.9%) and 77 (68.2%) tumor tissues exhibited positive immunohistochemical staining for Beclin-1 and ARID1A, respectively; 96 (85.0%) and 105 (92.9%) samples stained positive for CA9 and IDH1, respectively." (PMID 30849962, 2019). "ARID1A is generally considered as a tumor-suppressor gene because reduced expression of ARID1A has been found in a variety of tumors and correlated with tumor progression." (PMID 30849962, 2019). "In the Agilent microarray analysis, tumours with a high ARID1A signature were enriched in the luminal A and luminal B subgroups compared to the basal‐like subtype." (PMID 29392887, 2018). "ARID1A, a component of the SWI/SNF chromatin remodeling complex, is a tumor suppressor with a high frequency of inactivating mutations in many cancers." (PMID 30097580, 2018). "ARID1A is a recently identified tumor suppressor participating in forming SWI/SNF chromatin complexes." (PMID 29451900, 2018). "The mutations in ARID1A and POLE, and the fact that they were somatic, were confirmed by Sanger sequencing of DNA of tumor and normal tissues from the corresponding patients." (PMID 29599905, 2018). "Along with p21, cyclins, and E2F-responsive genes, ARID1A is essential for normal cell cycle arrest; thus, inactivation of ARID1A results in tumor transformation, metastasis, and/or drug resistance." (PMID 29540744, 2018). "ARID1A mRNA levels in TNBC tumours derived from patients with nCR are significantly lower than that of patients with pCR." (PMID 29392887, 2018). "Multivariate Cox regression analysis with tumor related death as endpoint for ARID1A/ß-Catenin status." (PMID 29451900, 2018). "Recent functional experiments have provided evidence that the ARID1A gene acts as a tumor suppressor." (PMID 29389895, 2018). "AURKAi treatment did not affect the growth of ARID1A wild-type tumor xenografts, but it significantly inhibited the growth of ARID1A−/− tumor xenografts at the same dosage." (PMID 30097580, 2018). "Mice bearing ARID1A isogenic tumors on either flank were given AURKAi via intraperitoneal (i.p.)injection, and the tumor volumes were measured periodically." (PMID 30097580, 2018). "Genome-wide sequencing analyses of tumor samples revealed that 46–57% of OCCC cases harbored loss-of-function mutations in the ARID1A gene, implying the significant contribution of aberrant ARID1A functions to OCCC pathogenesis." (PMID 30097580, 2018). "GSK126, a highly specific EZH2 inhibitor, caused the regression of established ARID1A-mutated OCCC and decreased the number of disseminated tumor nodules in xenograft models." (PMID 29599905, 2018). "A variety of neoplasms have been discovered to have genomic alterations and loss of immunohistochemical (IHC) expression of chromatin remodelers ARID1A (BAF250A), SMARCA2 (BRM), SMARCA4 (BRG1), and SMARCB1 (INI1)." (PMID 31093468, 2018). "It was noteworthy that the function of ARID1A was relevant to two processes of tumor development: proliferation and migration." (PMID 29317648, 2018).
tumor (continued). "The in-frame indel (Q1334del/dup), which increases the amount of the ARID1A protein in the nucleus and restores its tumor suppressor functions, has also been reported in GC samples." (PMID 29050249, 2017). "The relative abundance of ARID1A may partially account for its dominant role in tumor suppression, although complex composition and/or unique regulatory interactions of ARID1A-containing complexes may also contribute to the selective advantage of ARID1A mutations in human cancer." (PMID 28967863, 2017). "Tumor suppressor potential of ARID1A has been reported, in accordance with the relatively favorable prognostic roles of the MN_hi signature." (PMID 28984200, 2017). "Since the percentage of the mutation suggested a heterozygous alteration, the sustained immunohistochemical staining is probably due to wild-type ARID1A expressed in the tumour samples." (PMID 28103826, 2017). "In our molecular analysis, we detected and verified mutations in genes such as ARID1A, CTNNB1, PIK3CA, and PTEN which are frequently affected in these tumour entities." (PMID 28103826, 2017). "Tumor #7 from the stage 1 group provided an example: the SMARCA2 loss was a truncal event, PBRM1 loss was a branch event, while ARID1A and SMARCA4 losses were branch events that happened even later." (PMID 28445125, 2017). "Our results demonstrate that maintenance of chromatin accessibility is central to the tumor suppressor function of ARID1A." (PMID 28967863, 2017). "ARID1A has emerged from molecular and genomic studies as an important candidate and tumour suppressor in gynaecological malignancies." (PMID 27920066, 2017). "For ARID1A and SETD2, the statistically significant associations between marker losses and tumor stages would have been missed if truncal loss analysis were not performed." (PMID 28445125, 2017). "According to the results of somatic variants, the Q1334del/dup (n=23/52) in ARID1A and L15del (n=6/13) in CDH1 were detected at a frequency of 5∼33% of altered alleles in tumor tissue." (PMID 29050249, 2017). "Subgroup analyses were stratified according to ethnicity, disease location, Epstein-Barr virus (EBV) infection rate, TNM staging, tumor differentiation, status of MSI, ARID1A deficiency rate and sample size." (PMID 27354232, 2016). "A significant inverse correlation between miR-31 expression and ARID1A expression was found using the HNSCC tumor samples." (PMID 27528032, 2016). "We demonstrate that defects in ARID1A sensitize tumour cells to clinical inhibitors of the DNA damage checkpoint kinase, ATR, both in vitro and in vivo." (PMID 27958275, 2016). "Induction of the tumor suppressor, AT-Rich Interaction Domain 1A (ARID1A), increases occupancy of H3K9me3 at transcription start site (TSS) of hTERT and decreases acetylated lysine-12 of histone H4 (H4K12Ac) levels at this site." (PMID 27548225, 2016). "Overall, 22.6% of tumours harboured a coding mutation in one of the seven Mut-driver genes involved in chromatin function (KMT2C, ARID1A, NCOR1, CTCF, KDM6A, PRBM1 and TBL1XR1)." (PMID 27161491, 2016). "Specifically, ARID1A levels were reduced in 12.5% of the tumor tissues, whereas RUNX3 levels were lower in 87.5% of the tumor tissues analyzed." (PMID 27566570, 2016). "This in vivo assay strengthen the notion that the single gene depletion of ARID1A would promote tumor formation." (PMID 27323812, 2016). "Here, we found that depletion of endogenous ARID1A enhanced the in vitro proliferation, colony formation, cellular growth, nutrient uptake and in vivo xenograft tumor growth of GC cells." (PMID 27323812, 2016).
tumor (continued). "In ARID1A mutant tumour cells, inhibition of ATR triggers premature mitotic entry, genomic instability and apoptosis." (PMID 27958275, 2016). "VX-970 treatment also had a greater impact on ARID1A−/− tumours compared withARID1A+/+ tumours (P=0.006, ANOVA)." (PMID 27958275, 2016). "ARID1A gene emerges as a bona fide tumor suppressor, while its function and molecular mechanism in GC remains elusive." (PMID 27323812, 2016). "For example, alterations in PIK3CA and ARID1A were early events in tumour S13T2 (clonality >60%), but were detectable in <35% of cells in S13T1." (PMID 27377421, 2016). "We also determined the in vivo efficacy of VX-970 in mice with established tumours derived from a tumour cell line with naturally occurring ARID1A mutations (TOV21G, ARID1A p.548fs/p.756fs)." (PMID 27958275, 2016). "To do this, we generated cohorts of mice with established xenograft tumours derived from either HCT116 ARID1A+/+ or ARID1A−/− cells." (PMID 27958275, 2016). "In order to elucidate the role of RUNX3 as a TSG we evaluated the expression of ARID1A, a well-known TSG; ARID1A expression was lost in 12.5% of the tumor samples, which agrees with previously published results." (PMID 27566570, 2016). "It has been found that low expression of the ARID1A protein occurs in high frequency in many cancers and considered as a bona fide tumor suppressor." (PMID 26909602, 2016). "The present study identifies ARID1A to be a tumor suppressor and a tumor stemness repressor in HNSCC cells." (PMID 27528032, 2016). "For instance, in tumor 5 from our stage I group, losses of ARID1A and BRM were each detected in the first three foci, whereas losses of PBRM1 and BRG1 occurred only in the third focus (left)." (PMID 27764136, 2016). "We subcutaneously transplanted the same amount of Control shRNA and ARID1A shRNA cells into nude mice respectively; thereafter we monitored the tumor growth over a 8-week period." (PMID 25975202, 2015). "ARID1A knockdown promotes cell cycle progression, cell proliferation, tumorigenicity, migration, invasion and metastasis, whereas ARID1A overexpression inhibits cell proliferation and tumor growth." (PMID 26569409, 2015). "When comparing protein expression with their paired-control sample, ARID1A levels were lower in 42.4% of the tumor tissues whereas c-MET and PIK3CA levels were higher in 36.4% and 63.6% of the tumor tissues analyzed." (PMID 26334097, 2015). "Although ARID1A has been established as a tumor suppressor gene through the discovery of recurrent inactivating ARID1A mutations in a broad spectrum of cancers, its prognostic role is still debated." (PMID 26384299, 2015). "We evaluated the clinical implications of decreased ARID1A expression in HCC, and investigated the mechanisms of ARID1A-mediated tumor suppression." (PMID 25975202, 2015). "Previous in vitro experiments supported the idea that ARID1A/BAF250a exerts a tumor suppressive effect." (PMID 26569409, 2015). "To further investigate the role of ARID1A in GC, we performed IHC analysis of ARID1A in 33 paired-tumor samples." (PMID 26334097, 2015). "Recent studies have identified AT-rich interactive domain-containing protein 1A (ARID1A) as a broad-spectrum tumor suppressor." (PMID 25975202, 2015). "In conclusion, ARID1A deficiency leads to a significantly increased sensitivity towards PI3K- and AKT-inhibition in tumor cells in vitro." (PMID 24979463, 2014).
tumor (continued). "Knockdown of BAF250a by siRNA in three CCC cell lines wild type for ARID1A showed no increase in either pAKT-Thr308 or pAKT-S473 suggesting that pAKT in tumor tissues is indirectly regulated by BAF250a expression." (PMID 24559118, 2014). "NGS performed on a tumor sample from the liver biopsy obtained at the time of diagnosis revealed CDKN2A mutation A102P, ARID1A mutation I1485fs*5, CCND1 amplification, FGF19 amplification, FGF3 amplification and FGF4 amplification." (PMID 24931142, 2014). "In AC, mutations were found in tumor suppressors SMARCA4/BRG1 (SWI/SNF-related, matrix-associated, actin-dependent regulators of chromatin) and ARID1A (AT-rich interaction domain 1A) – both members of the SWI/SNF complex, in 8% and 10% of tumors, respectively." (PMID 24722523, 2014). "The role of BAF250a/ARID1A in cell-cycle repression implies that it contributes significantly to the tumor suppression activities of SWI/SNF complexes." (PMID 23349767, 2013). "The contribution of different reasons to ARID1A low expression is different in different kind of tumor." (PMID 23349767, 2013). "Exome sequencing has identified ARID1A as a novel tumor suppressor gene coding for a chromatin remodeling protein that is mutated in UBC." (PMID 23650517, 2013). "Although the subject of intensive study, the exact function and role of ARID1A as a tumor suppressor remains far from being elucidated." (PMID 24036443, 2013). "We recently identified a truncating ARID1A mutation through UBC exome sequencing and a manuscript recently described the occurrence of ARID1A mutations in this tumor." (PMID 23650517, 2013). "In vitro studies have suggested different roles for ARID1A to exert its tumor suppressive action, which are mainly through proliferation, differentiation and apoptosis." (PMID 24036443, 2013). "Similar observations in other cancer types, as well as results of in vitro studies, therefore, suggest a haploinsufficient tumor suppressor role for ARID1A." (PMID 24036443, 2013). "The majority of these mutations lead to a loss of expression of the ARID1A protein, which is a subunit of the SWI/SNF chromatin remodeling complex and considered as a bona fide tumor suppressor." (PMID 24036443, 2013). "Given that, it is now known that ARID1A is a bona fide tumor suppressor gene in OCCC, we applied this principle to the evaluation of ARID1A mutations in other tumor types." (PMID 22009941, 2012). "We studied more than 700 different neoplasms of seven different types using Sanger sequencing to determine the contribution of ARID1A alterations to tumorigenesis in general." (PMID 22009941, 2012). "ARID1A mutations, which occur in approximately half of OCCC cases, lead to deletion of the encoded protein and inactivation of the putative tumor suppressor." (PMID 21614196, 2010). "ARID1A is located within chromosome 1p36, a region frequently deleted in a variety of human neoplastic diseases including OCCC." (PMID 21614196, 2010). "Notably, consistent with the function of ARID1A in other cancer types (including gastric, lung and renal cancers), it acts as a tumour suppressor gene in CCA." (PMID 41578412, 2026). "Furthermore, ARID1A promotes tumour growth in the early stages of the tumour, but after the tumour has established, its heterozygous and pure deletion speeds up the progression of HCC and metastases." (PMID 41578412, 2026).
tumor (continued). "ARID1A has been previously reported to maintain acinar homeostasis and prevent PDAC transformation in engineered mouse models, while loss of TGFBR2 contributes to tumor development mainly through the TGF-β signaling pathway." (PMID 41480763, 2026). "While concurrent mutations in their encoding genes (ARID1A and ARID1B) may co‐occur in tumours, a synthetic lethal interaction between these paralogs has been identified, wherein ARID1B deficiency selectively eliminates ARID1A‐mutant cancer cells." (PMID 41578412, 2026). "This shows that p21 is a key mediator of ARID1A’s tumor-suppressive function." (PMID 40429787, 2025). "We then stratified CRC patients into two subgroups based on the tumor ARID1A expression." (PMID 40750787, 2025). "This dual profile may also inform treatment, as ARID1A-deficient tumours respond to DNA-damaging agents and immune checkpoint inhibitors, while ATM loss may sensitize tumours to PARP or ATR inhibitors." (PMID 41146957, 2025). "In fact, loss of ARID1A might enhance oncogenic signaling, such as PI3K/AKT activation, leading to tumor growth." (PMID 41514650, 2025). "Pb-Cre;Ptenfl/flArid1afl/+ tumours only had 183 significantly dysregulated genes compared to Pb-Cre;Ptenfl/fl, indicating a single copy loss of Arid1a does not cause large transcriptional changes." (PMID 39885328, 2025). "Arid1aINT bearing tumours had a 64% reduction in Arid1a expression (p < 0.0001)." (PMID 39885328, 2025). "High tumor mutational burden (TMB) is associated with immunotherapy, and several genes related to high TMB, including ARID1A, RNF43, BRAF, and KM2B in microsatellite instability (MSI) tumors, may also be used for the treatment of MSS patients." (PMID 40242245, 2025). "Furthermore, we discovered that ARID1A exerted a tumor-suppressive function through transcriptional suppression of c-MYC and PARP1." (PMID 41049615, 2025). "We and others recently identified ARID1A as a 1p36 gene that is an N-MYC tumor suppressor 20,21." (PMID 40082458, 2025). "In various mouse models of liver cancer, ARID1A has been shown to exhibit tumor-promoting activity by promoting early transformation, potentially through regulation of oxidative stress pathways mediated by the cytochrome P450 (CYP450) system, which generates reactive oxygen species (ROS)." (PMID 41514650, 2025). "This proposed mechanism would position ARID1A as a tumor suppressor in this context." (PMID 41001036, 2025). "Overall, these data suggest that the presence of ARID1A alterations may predict sensitivity to ICI therapy across multiple tumor types." (PMID 41387924, 2025). "ARID1A has emerged as a critical tumor suppressor in cancer research." (PMID 41001036, 2025). "In an in vivo experiment using engineered mice harboring ARID1A loss and PIK3CA mutations, treatment with the PIK3 inhibitor buparlisib led to a dose-dependent reduction in AKT levels and tumor viability, highlighting the therapeutic potential of buparlisib in OCCC with these co-mutations." (PMID 41514650, 2025). "We next investigated whether the status of ARID1A and PTEN in clinical tumours was associated with patient outcomes." (PMID 39885328, 2025). "This bidirectional crosstalk could amplify genomic instability, ultimately driving tumor progression in the ARID1A-hypermethylated GC molecular subset." (PMID 41215803, 2025). "Furthermore, mutations in the AT-rich interaction domain 1A (ARID1A) gene have been associated with microsatellite instability and increased tumor mutation load." (PMID 40658469, 2025).